MIR648 (microRNA 648)
Synonyms: hsa-mir-648; MIRN648
Gene: MicroRNA gene on chromosome 22 (17,980,868 to 17,980,961, reverse strand). Ensembl gene ENSG00000207780.
Gene Ontology:
Biological process: miRNA-mediated post-transcriptional gene silencing
Cellular component: RISC complex